CACNA1D (calcium voltage-gated channel subunit alpha1 D)
Description:
Voltage-sensitive calcium channels (VSCC) mediate the entry of calcium ions into excitable cells and are also involved in a variety of calcium-dependent processes, including muscle contraction, hormone or neurotransmitter release, gene expression, cell motility, cell division and cell death. The isoform alpha-1D gives rise to L-type calcium currents. Long-lasting (L-type) calcium channels belong to the 'high-voltage activated' (HVA) group. They are blocked by dihydropyridines (DHP), phenylalkylamines, and by benzothiazepines. [Isoform Neuronal-type]: Voltage-sensitive calcium channels (VSCC) mediate the entry of calcium ions into excitable cells and are also involved in a variety of calcium-dependent processes, including muscle contraction, hormone or neurotransmitter release, gene expression, cell motility, cell division and cell death. The isoform alpha-1D gives rise to L-type calcium currents. [Isoform 3]: Voltage-sensitive calcium channels (VSCC) mediate the entry of calcium ions into excitable cells and are also involved in a variety of calcium-dependent processes, including muscle contraction, hormone or neurotransmitter release, gene expression, cell motility, cell division and cell death. The isoform alpha-1D gives rise to L-type calcium currents. [Isoform 4]: Voltage-sensitive calcium channels (VSCC) mediate the entry of calcium ions into excitable cells and are also involved in a variety of calcium-dependent processes, including muscle contraction, hormone or neurotransmitter release, gene expression, cell motility, cell division and cell death. The isoform alpha-1D gives rise to L-type calcium currents.
Synonyms: CACH3; CACN4; CACNL1A2; CCHL1A2; Cav1.3; PASNA; SANDD
Tractability: Small molecule: an approved drug acts on it; a structure with a bound ligand is known; a high-quality ligand is known; it belongs to a druggable protein family. Antibody: its Gene Ontology location is reachable by antibodies, with high confidence; UniProt predicts a signal peptide or a membrane-spanning region. PROTAC: a small molecule that binds it is known.
Target class: Voltage-gated calcium channel; Ion channel; Voltage-gated ion channel
Gene: Protein-coding gene on chromosome 3 (53,328,963 to 53,813,733, forward strand). Ensembl gene ENSG00000157388.
Subcellular location: Membrane
Subcellular location (Human Protein Atlas): Nuclear membrane
Pathways (Reactome):
Metabolism: Adrenaline,noradrenaline inhibits insulin secretion; Regulation of insulin secretion
Developmental Biology: NCAM1 interactions
Sensory Perception: Sensory processing of sound by inner hair cells of the cochlea
Gene Ontology:
Molecular function: alpha-actinin binding; calcium channel activity; high voltage-gated calcium channel activity; protein binding; voltage-gated calcium channel activity; voltage-gated calcium channel activity involved SA node cell action potential; ankyrin binding; voltage-gated calcium channel activity involved in cardiac muscle cell action potential; cytoskeletal protein binding; monoatomic ion channel activity; voltage-gated calcium channel activity involved in regulation of presynaptic cytosolic calcium levels
Biological process: calcium ion import; calcium ion transport; cardiac muscle cell action potential involved in contraction; membrane depolarization during SA node cell action potential; positive regulation of calcium ion transport; regulation of heart rate by cardiac conduction; sensory perception of sound; adenylate cyclase-modulating G protein-coupled receptor signaling pathway; calcium ion import across plasma membrane; calcium ion transmembrane transport; membrane depolarization during cardiac muscle cell action potential; positive regulation of adenylate cyclase activity; regulation of atrial cardiac muscle cell membrane repolarization; regulation of potassium ion transmembrane transport; cell communication; monoatomic ion transport; muscle contraction; nervous system process; positive regulation of transport; regulation of metal ion transport; regulation of presynaptic cytosolic calcium ion concentration; transmembrane transport
Cellular component: L-type voltage-gated calcium channel complex; membrane; voltage-gated calcium channel complex; plasma membrane; Z disc; cochlear hair cell ribbon synapse; presynaptic active zone membrane; synaptic ribbon; T-tubule
Genetic constraint (gnomAD): Loss-of-function variants: 41 observed, 210.62 expected, observed/expected ratio (o/e) 0.19, 90% interval 0.15 to 0.25. The upper end of that interval is the gene's LOEUF score, 0.25, which puts it in group 1 of 6, group 1 being the genes least tolerant of losing a copy. Missense variants: 1,669 observed, 2,592.6 expected, observed/expected ratio (o/e) 0.64, 90% interval 0.62 to 0.67. Synonymous variants: 880 observed, 955 expected, observed/expected ratio (o/e) 0.92, 90% interval 0.87 to 0.97.
Gene-disease validity (ClinGen):
ClinGen rates the evidence that CACNA1D causes each of these diseases.
complex neurodevelopmental disorder (autosomal dominant): Definitive. A disorder that involves more than one phenotype associated with the central nervous system, including but not limited to intellectual disability, autism, and seizures (epilepsy).
sinoatrial node dysfunction and deafness (autosomal recessive): Moderate.
Cancer hallmarks: proliferative signalling (promotes)
Homologues: Orthologues: chimpanzee CACNA1D (99% identical), macaque CACNA1D (99% identical), pig CACNA1D (98% identical), dog CACNA1D (97% identical), rat Cacna1d (97% identical), mouse Cacna1d (96% identical), guinea pig CACNA1D (96% identical), rabbit CACNA1D (94% identical), tropical clawed frog cacna1d (82% identical), zebrafish cacna1da (75% identical). Paralogues in human: CACNA1C (66% identical), CACNA1F (62% identical), CACNA1S (56% identical), CACNA1A (38% identical), CACNA1B (38% identical), CACNA1E (37% identical), CACNA1H (24% identical), CACNA1I (23% identical), CACNA1G (23% identical), SCN2A (22% identical), SCN9A (22% identical), SCN3A (22% identical), and 14 more.
Diseases named in the same sentence as CACNA1D in open-access papers:
CACNA1D is named in the same sentence as 159 diseases in open-access papers, as found by Europe PMC text mining. Sharing a sentence is not in itself a finding about the gene and the disease. The quoted sentences say what the papers report.
deafness (37 papers, 2012 to 2025). An inherited or acquired condition characterized by the complete loss of the ability to hear from one or both ears. "Similar to CACNA1D knockout mice, human CACNA1D mutations cause clinical manifestations of deafness and bradycardia, a condition known as SANDD syndrome." (PMID 39365143, 2024). "So far, homozygous loss of function mutations in CACNA1D encoding the Cav1.3 α1-subunit are described in congenital sinus node dysfunction and deafness." (PMID 36430690, 2022). "To date, no studies have been conducted in the Pakistani population to investigate the genetics underlying the cardiac system, except for a report of a homozygous mutation in CACNA1D, which causes deafness with bradycardia syndrome." (PMID 34440456, 2021). "As CACNA1D mutations have been previously implicated in deafness in humans, mice and even zebrafish, we assessed the hearing sensitivities of larvae across genotypes using different stimulus intensities (sound) and found them to be comparable." (PMID 33057948, 2021). "CACNA1D knockout mice (the gene encoding Cav1.3) exhibit congenital deafness." (PMID 41169615, 2025). "While the loss of CaV1.3 function causes syndromic deafness, the CACNA1D p.A749G mutation belongs to a group of mutations that cause aberrant gating and often are associated with neurodevelopmental disorders with and without endocrine symptoms but so far uncertain hearing function." (PMID 40532010, 2025). "mutation in CACNA1D may cause both sinoatrial node dysfunction and deafness (termed SANDD syndrome) in mice and in humans, in humans closely resembling that of Cacna1d−/− mice." (PMID 36769387, 2023). "With respect to the severity of the cardiac phenotype and the occurrence of deafness, the phenotypic expression of CACNA1D mutations resembles the phenotypic spectrum seen in loss-of-function mutations in the KCNQ1 gene encoding the α1-subunit of the cardiac potassium channel Kv7.1." (PMID 36430690, 2022). "RIMBP2 is a member of a family of proteins that act as binding partners of the presynaptic active zone proteins RIMs as well as for voltage-gated Ca2+-channels, such as CACNA1B and CACNA1D, the latter already known to be involved in deafness." (PMID 24454846, 2014). "We recently demonstrated an essential retrocochlear function of the peripheral deafness gene Cacna1d for the development of the auditory brainstem." (PMID 23152916, 2012). "In addition, Cav1.3 also plays an important role in calcium homeostasis in the ear, as cacna1d–/– mice experience deafness along with SND." (PMID 33868385, 2021). "In humans, loss of function mutations in CaV1.3 (CACNA1D) results in Sinoatrial Node Dysfunction and Deafness (SANDD), a disorder whereby affected individuals have abnormal heart rhythms and severe deafness." (PMID 30258843, 2018). "In 2010 the first homozygous loss-of-function mutation (p.Gly403dup) in the CACNA1D gene was described in a consanguineous Pakistani family with congenital deafness and sick sinus syndrome; this complex and syndromal disease was termed ‘SANDD’ (sinoatrial node dysfunction and deafness)." (PMID 36430690, 2022). "Segdups, defined as regions with > 95% homology, are features that are causally implicated in recurrent CNVs mediated by NAHR and were identified in seven deafness genes: TSPEAR (4 segdups), OTOA, STRC, MYO3A, ESPN, OTOGL, CACNA1D." (PMID 24963352, 2014). "Interestingly, contrary to a published Cacna1d-KO model with deafness, bradycardia, and impaired motor performance, our Cacna1d–/– mice were not viable." (PMID 37698934, 2023). "This is strongly supported by previous findings both in knockout mice and Cav1.3-deficient humans with sinoatrial node dysfunction and deafness (SANDD; OMIM #614896), in which functional loss of one or both CACNA1D alleles did not lead to a central nervous system (CNS) disease phenotype." (PMID 31921405, 2020).
Parkinson disease (31 papers, 2014 to 2025). A progressive degenerative disorder of the central nervous system characterized by loss of dopamine producing neurons in the substantia nigra and the presence of Lewy bodies in the substantia nigra and locus coeruleus. "CACNA1D gene variants have been recently identified in another neurodegenerative disease, namely in Parkinsonism." (PMID 36979911, 2023).
adenoma (21 papers, 2015 to 2025). A neoplasm arising from the epithelium. "A study by Nanba et al41 found that somatic CACNA1D (Calcium Voltage-Gated Channel Subunit Alpha1 D) mutations were the most prevalent genetic alteration in Black patients with aldosterone-producing adenomas, followed by KCNJ5 mutations." (PMID 40536937, 2025). "In 2013, we and others discovered heterozygous somatic gain-of-function mutations in the CACNA1D gene, encoding voltage-gated L-type calcium channel CaV1.3, as a cause of aldosterone-producing adenomas." (PMID 37698934, 2023). "Using CRISPR/Cas9, we here generated mice with a Cacna1d gain-of-function mutation found in both adenomas and PASNA syndrome (Cacna1dIle772Met/+)." (PMID 37698934, 2023). "In particular, ATP1A1 and CACNA1D mutations have been found in men with small adenomas." (PMID 33912136, 2021). "In addition, another genetic study found several polymorphisms of CACNA1D were associated with aldosterone-producing adenomas and primary aldosteronism, which is the most common curable cause of secondary hypertension." (PMID 31145748, 2019). "This prediction has been largely confirmed by the finding of gain-of-function somatic mutations affecting cation transport in most aldosterone-producing adenomas, and in particular the finding of multiple mutations affecting calcium influx in the gene, CACNA1D, encoding Cav1.3." (PMID 31564164, 2019). "Within T-DNA, somatic variants were identified in 53% of adenomas: PRKACA in 2/7 CPA-CS, CTNNB1 in 3/5 CPA-MACS and 1/7 CPA-CS, KCNJ5 in 2/5 APA and CACNA1D in 1/5 APA." (PMID 39891827, 2025). "The observed pathological variants of aldosterone-producing adenomas in our cohort were KCNJ5 (N=5), ATP1A1 (N=5), and CACNA1D (N=4) mutations." (PMID 39897961, 2024). "Several somatic mutations have been found in aldosterone-producing adenomas in KCNJ5, ATP1A1, ATP2B3, CACNA1D, and CTNNB1 genes." (PMID 32783015, 2020). "At the molecular level, somatic mutations involving potassium channels (KCNJ5), ATPases (ATP1A1 and ATP2B3), and calcium channels (CACNA1D) account for approximately 60% of sporadic aldosterone-producing adenomas." (PMID 29594118, 2018). "Several lines of evidence suggest that KCNJ5-mutant aldosterone-producing adenomas have distinct clinicopathological phenotype compared to those harboring ATP1A1, ATP2B3, and CACNA1D mutations." (PMID 29594118, 2018). "Targeted sequencing for the reported mutations in APAs of KCNJ5, CACNA1D, ATP1A1, ATP2B3 and CTNNB1 exons was performed from the adenomas." (PMID 28102204, 2017). "Furthermore, somatic mutations in other genes, such as KCNJ5, CACNA1D, and ATP1A1, have been implicated in aldosterone-producing adenomas, highlighting the complex genetic landscape of adrenal tumors." (PMID 41007858, 2025). "In the last decade, somatic pathogenic variants in KCNJ5, CACNA1D, ATP1A1 and ATP2B3 genes, which are involved in maintaining intracellular ionic homeostasis and cell membrane potential, were described in aldosterone-producing adenomas (aldosteronomas)." (PMID 35813615, 2022). "Moreover, we have used Sanger sequencing to confirm that there were no other conventional and well-characterized aldosterone-driving gene mutations, including KCNJ5, ATP1A1, CACNA1D, and CTNNB1, in the adenoma harboring with ATP2B3 K416_F418delinsN mutation." (PMID 34572956, 2021). "However, somatic mutations resulting in the corresponding substitutions I1430T in Cav3.2 (CACNA1H) and I1015S/V in Cav1.3 (CACNA1D) were identified in aldosterone-producing adenomas." (PMID 33704440, 2021). "In contrast, tumors that are composed predominantly of ZG-like compact cells are typically enriched in ATP1A1-, ATP2B3-, and CACNA1D-mutant aldosterone-producing adenomas that show increased and strong CYP11B2 expression and predominantly negative CYP11B1 or CYP17A1 expression profiles." (PMID 29594118, 2018).
adenoma (continued). "Our analysis of mutation V401L revealed the characteristic gating changes, allowing enhanced Ca2+ entry, as observed in the previously reported germline CACNA1D mutations in two patients with ASD and in individuals with PASNA as well as in somatic mutations in aldosterone-producing adenomas." (PMID 28472301, 2017). "In addition, ~60% of micronodules from patients with PA without adenomas and ~25% of micronodules from apparently healthy adrenal glands carry somatic CACNA1D mutations." (PMID 37698934, 2023).
primary aldosteronism (18 papers, 2015 to 2025). An endocrine disorder characterized by excessive production of aldosterone by the adrenal glands. "While some CACNA1D mutations are linked to primary aldosteronism, others are associated solely with neurological manifestations without affecting aldosterone regulation." (PMID 40243517, 2025). "Second, identification of CACNA1D as the causative gene was important because it guided the further clinical diagnosis of primary aldosteronism and hypertension." (PMID 32336187, 2020). "Several studies have confirmed the tumorigenic role of this mutation as it was mutually exclusive to ion channel-related (KCNJ5, ATP1A1, ATP2B3, and CACNA1D) mutations in primary aldosteronism." (PMID 29594118, 2018). "CACNA1D mutations have previously been associated with primary aldosteronism, seizures, and neurologic abnormalities (PASNA; OMIM #615474), thus suggesting a disease spectrum that may include CHI with reduced penetrance." (PMID 37065762, 2023). "Indeed, activating Cav1.3 missense mutations associated with CNS disorders were first discovered in whole exome sequencing studies identifying a causal role of CACNA1D mutations for primary aldosteronism." (PMID 26842699, 2016). "Primary aldosteronism can also be caused by mutations in ATP2B3 (Ca2+-ATPase), CACNA1D (Cav1.3), and KCNJ5 (K+ channel)." (PMID 27313535, 2016). "The identification of two de novo gain-of-function missense mutations in CACNA1D in two patients with primary aldosteronism, seizures and neurological abnormalities (PASNA, OMIM: 615474), further points to the involvement of altered Cav1.3 function in neurological disorders." (PMID 28472301, 2017). "Indeed, whole exome sequencing studies, originally prompted to identify mutations in primary aldosteronism, revealed de novo CACNA1D missense mutations permitting enhanced Ca2+ signalling through Cav1.3." (PMID 26842699, 2016). "Indeed, a proportion of patients with primary aldosteronism are now known to harbor adrenal cortical adenomas with heterogeneous molecular alterations (KCNJ5, ATP1A1, ATP2B3, and CACNA1D) involving the calcium/calmodulin kinase signaling pathway." (PMID 29594118, 2018).